IL10 (interleukin 10)
Diseases named in the same sentence as IL10 in open-access papers (continued):
Sharing a sentence is not in itself a finding about the gene and the disease.
helminth infections (continued). "Regulatory cytokine IL-10 has been shown to play an important role in control of allergic airway disease by helminth infections or by helminth-derived products." (PMID 23844022, 2013). "In chronic human and experimental infections, Schistosoma mansoni, like all helminth infections, induces a predominantly Th2 immune response, characterized by interleukin-4, IL-5, IL-9, IL-10 and IL-13, antibody (IgE and IgG4), eosinophils and mast cells." (PMID 23849678, 2013). "Chronic helminth infections generally induce multiple regulatory pathways, involving regulatory T cells, B cells, dendritic cells, and macrophages, with IL-10 and TGF-β playing an important role." (PMID 23844022, 2013). "In the past few years, it has been shown that chronic helminth infections or parasite products induce the production of T-regulatory cells and molecules such as IL-10." (PMID 22934153, 2012). "Prior studies from our group and others have demonstrated increased plasma levels of IL-10, as well as increases in regulatory T cell frequency and function, in children and young adults with helminth infection." (PMID 23133692, 2012). "In summary, our data describe a role for IL-10-dependent B cell responses in the regulation of tissue damage during a chronic helminth infection." (PMID 22291593, 2012). "Previous studies have also demonstrated that following helminth infection, Bregs promote Treg expansion by secreting IL-10." (PMID 23071588, 2012). "On the other hand, IL-10, the major anti-inflammatory cytokine and the product of alternatively activated macrophages (M2), which characterizes helminthes infection, is largely produced." (PMID 23285072, 2012). "Induction of IL-10 as an immunosuppressive cytokine is a common phenomenon found in chronic helminth infections." (PMID 21253577, 2011). "We previously demonstrated the role of helminth infections or isolated helminth proteins in suppressing bystander immune responses in mouse models of allergy and colitis via a macrophage and IL-10 dependent mechanism." (PMID 21253577, 2011). "More specifically, helminth infections tend to promote a type 2 bias in the immune response, involving the production of the cytokines interleukin-4 (IL-4), IL-5, IL-10, and IL-13, as well as immunoglobulin E." (PMID 17083720, 2006). "Recent evidence also highlights IL-10 as a central regulator during chronic helminth infection." (PMID 41567205, 2025). "The increased Th2 regulation in leprosy patients with helminth infections is considered to be the cause of raised IL-10 and indirectly also increases IL-6 levels in leprosy with helminth infections compared to those without helminth infections." (PMID 41239264, 2025). "Blocking IL-10 was found to partially restore vaccine responses, suggesting that targeting IL-10 might improve vaccine effectiveness in individuals with helminth infections." (PMID 40432048, 2025). "Helminth infections are well known to induce Th2 and regulatory immune polarization, characterized by increased IL-4, IL-5, IL-10, and IL-13 production and expansion of T regulatory cells, which suppress Th1/Th17 effector responses critical for antimycobacterial immunity." (PMID 41583474, 2025). "Helminth infections also make the immune system weaker by increasing the number of Tregs (immunological regulatory monocytes) and the cytokines transforming growth factor beta (TGFβ) and interleukin 10 (IL-10)." (PMID 40460141, 2025). "Helminth infections are considered natural models of immune tolerance, primarily mediated by the induction of regulatory T cells and the production of anti-inflammatory cytokines such as IL-10 and TGF-β." (PMID 39312581, 2024). "Hence, IL-10 levels are higher in helminth infection since these parasites have mechanisms of evading the immune system to ensure long-term survival within the host." (PMID 37513018, 2023).
helminth infections (continued). "Alternatively, IL-4 and IL-10 present in the spleen during helminth infection may act directly on antigen-specific Th cell differentiation after immunization and block Th17 and Th1 bias." (PMID 36753434, 2023). "Furthermore, IL-10 production promotes the downregulation of Th1 cells, NK cells and macrophages and suppresses Th1/Th17 during helminthic infection." (PMID 37600806, 2023). "Protection against helminth infection is predominantly mediated by Th2 cells, characterized by the production of cytokines such as IL-4, IL-5, IL-10, and IL-13; antibody class-switching to produce IgE; and activation of macrophages, eosinophils, basophils, and mast cells." (PMID 37020538, 2023). "The type 2 immune response at the site of intestinal helminth infection maintains the stimulates of Th2 effector cells and T regulatory cells, which may lead to higher IL-10 levels in the intestine than in the spleen." (PMID 36187827, 2022). "In summary, we have shown that IL-10 promotes the intestinal Th2 response to a helminth infection." (PMID 35428872, 2022). "In onchocerciasis patients spontaneous cellular IL-10 production has been observed, and mf and antigens emerging from adult O. volvulus and concurrent helminth infections may stimulate IL-10." (PMID 35503786, 2022). "The conversion from classical monocytes to non-classical monocytes may be due to an increased production of IL-10 and TGF-β, which is usually associated with helminth infections." (PMID 33651797, 2021). "This becomes important where asymptomatic helminth infection profoundly affects the immune phenotype of TB patients with a strong bias towards Th2 types of immune response, such as increased regulatory T cells as well as IL-5 and IL-10 secreting cells." (PMID 32498074, 2020). "IL-10 and TGFβ1 are T-regulatory cytokines that are important in regulating the immune response, and they play a major role in minimizing the pathology and boosting tissue repair during helminth infections." (PMID 32636589, 2020). "Th2, Tregs, and the immunoregulatory cytokines they produce (such as interleukin-4 [IL4], IL10, and TGFβ) generated during helminth infection may act as potent inhibitors of the Th1 responses which are required for immunity against Mtb infection." (PMID 32498074, 2020). "For example, it was shown that various helminth infections induce IL-10-producing Breg populations which were shown to be antigen-specific during chronic schistosomiasis, but the distinct role of Breg populations during W. bancrofti infection has remained largely unclear." (PMID 31120872, 2019). "When subjects were free of helminth infection (helminth-negative), increasing proportions of Bacteroidetes was associated with lower levels of IL-10 response to LPS {estimate [95% confidence interval (CI)] −1.96 (−3.05, −0.87)}." (PMID 31781154, 2019). "For example helminth and malaria co-infections, which are common in Nigeria, are associated with IL-10 responses and a skewing to Th2 response to mTB, but we did not evaluate helminth infections in our infant cohort." (PMID 31649662, 2019). "Little is known about Breg populations in helminth infection and so far only a few studies have shown that Breg subsets which produce IL-10 were increased in schistosome-infected individuals and might be important to modulate host immunity." (PMID 29324739, 2018). "In this investigation, rHc-AK significantly increased the secretion of IL-10 in goat PBMCs and could facilitate worm infection by inducing Treg cells to produce immunosuppressive cytokine IL-10." (PMID 28651566, 2017). "In the process of M2 polarization and helminth infection, the immune response of the host to helminth infections is strikingly dominated by a Th2 response with a significant production of IL-4, IL-10, IL-13, and the STAT3/STAT6 signaling pathways have been detected." (PMID 28983296, 2017).
helminth infections (continued). "In the context of helminth infection, parasite-induced IL-10 secretion may enhance the homeostatic capacity of the host including elevated generation of Tregs63." (PMID 28871165, 2017). "The cytokine profile results support that helminth infections generally polarize the T cell response towards Th2, while IL-10 and TGF-β might suppress Th1 response and therefore inhibit the production of IFN-γ." (PMID 27809931, 2016). "In human helminth infections, IL-10 is also a very prominent immunosuppressive factor; whether this is driven by high levels of TGF-β remains to be ascertained." (PMID 26617281, 2016). "We found that concomitant asymptomatic helminth infection profoundly affects the immune phenotype of TB patients with a strong leaning towards Th2 types of immune response such as increased regulatory T cells as well as IL-5 and IL-10 secreting cells." (PMID 26248316, 2015). "We found increased level of IL-10 associated with helminth infection in TB patients as compared to helminth negative TB patients." (PMID 26248316, 2015). "In the present study, the role of F4/80+MHC-IIhigh macrophage derived IL-10 might be important for the initial polarization of dermal CD4+ T cells towards their subsequent production of IL-10, as shown in another recent study of helminth infection." (PMID 25974019, 2015). "Helminth infections were associated in a dose-dependent way to decrease in the prevalence of SPT and increase in eosinophilia, total IgE, and the production of the regulatory cytokine IL-10 by unstimulated peripheral blood leukocytes." (PMID 25410903, 2014). "In the case of spontaneous cytokine production, IL-10, but none of the other cytokines, was associated with helminth infections, i.e., children with increasing number of infections were more likely to be IL-10 cytokine responders." (PMID 25410903, 2014). "On the other hand, helminth infections could induce activation of TReg cells, resulting in IL-10 and IgG4 production, hence attenuating TH2-immune responses and thus may modulate allergic inflammation." (PMID 25002754, 2014). "The increased stimulation of cross-reactive Tregs due to past or present helminth infections could explain the spontaneous production of IL-10 observed in the present study." (PMID 25410903, 2014). "On the other hand, anti-inflammatory/Th2 cytokines IL-4 and IL-10 may either be upregulated by previous helminthic infection, or as a homeostatic mechanism to buffer both production and effects of pro-inflammatory cytokines." (PMID 25303100, 2014). "An increase in IL-10 and transforming growth factor-β and a decrease in IL-12 and interferon-γ-secreting cells have been shown in fresh peripheral blood mononuclear cells (PBMCs) of MS patients with a helminth infection." (PMID 23782752, 2013). "IL-10 producing B cells (Bregs) are also involved in the recruitment of Tregs, hence contributing to the regulation of Th2 responses as demonstrated in murine models of helminth infection." (PMID 22970345, 2012). "Since the primary source of IL-10 in most helminth infections is the CD4+Foxp3− subset, it will also be interesting to identify whether schistosome immunity in this system is directly impeded by classical Tregs." (PMID 22795966, 2012). "The elevated production of IL-10 spontaneously during helminth infections could contribute to immune homeostasis by raising the threshold for the induction of effector inflammatory responses in the tissues." (PMID 21666788, 2011). "Similarly, in our study, helminth infection significantly elevated IL-10 levels while concurrently reducing decreased TNF-α expression, indicating that helminth infection protects against the HFD-induced abnormal lipid metabolism via activation of immune responses in teleost." (PMID 40708918, 2025).
helminth infections (continued). "While the relationship between parasite density and QFT positivity is not well established, some studies suggest that helminth infections are associated with increased levels of regulatory T cells and IL-10, which may suppress the Th1 response." (PMID 39435458, 2024). "Indeed, it was shown that helminth infections induce IL-10-producing Breg populations but the role of such immune cell subsets during filarial infection remains unclear." (PMID 31120872, 2019). "Although helminth infections are characterized by predominant type-2 immune response, they also stimulate an immune regulatory network response with production of anti-inflammatory cytokines, IL-10 and TGF-β, which modulate the immunopathology and facilitate parasite survival." (PMID 30713536, 2018). "This defective IL-10 production was subsequently confirmed by Correale and Farez21 who observed that helminth infections could restore normal IL-10 production by B cells in this disease, which correlated with an improvement of the disease course compared with non-infected patients." (PMID 27396388, 2016). "For this, helminth infections may be of particular value, as in vitro exposure of splenic B cells to live schistosome worms or peritoneal injection of schistosome egg-derived glycans or filarial glycoproteins induces IL-10-producing B cells." (PMID 22347409, 2012). "On the other hand, the alternative activation of macrophages is stimulated by macrophage colony-stimulating factor (M-CSF1, CSF1), IL-4, IL-10, transforming growth factor β (TGF-β), IL-13, and fungi or helminth infections, and leads to the M2 phenotype." (PMID 37958467, 2023). "Along the same line, blocking IL-10R or neutralizing IL-10 restores Th1 (IFN-γ, TNF-α) and Th17 (IL-17A, IL-17F) responses and ameliorates Mtb control that is blunted, respectively, by influenza A and helminth infection." (PMID 35113966, 2022). "Treg populations, “natural” Tregs and “induced” Tregs, are activated in an effort to dampen host immune response through production of IL-10 and TGF-β during helminthic infection." (PMID 33193446, 2020). "Treg cells and regulatory cytokines IL-10 and TGF-β participated in immune evasion of helminth infection by negative regulation of the host immune system." (PMID 31703440, 2019). "An up-regulation of IFN-γ during Plasmodium falciparum malaria and an up-regulation of IL-10 and TGF-β in soil borne helminth infections was demonstrated." (PMID 29560020, 2018). "Based on the observation that increased production of IL-10 by CD4+ T cells and B cells after helminth infection induced modulation of EAE and MS, it seems reasonable to postulate recombinant IL-10 use (rIL-10) for MS patient treatment." (PMID 22937527, 2012). "Meanwhile, the mean IL-10, IL-6, and leptin serum levels for leprosy without helminth infection were 72.97 pg/ml ± 14.69 pg/ml, 161.77 pg/ml ± 63.98 pg/ml, and 14,649.07 pg/ml ± 2,002.66 pg/ml, respectively." (PMID 41239264, 2025). "Helminth infection with Heligmosomoides polygyrus prevents type 1 diabetes (T1D) in nonobese diabetic mice by enhancing IL-10 production from CD4(+) T cells, with protection lasting up to 40 weeks." (PMID 40299229, 2025). "The non-significance of IL-10 in adjusted models presents an interesting paradox, given its well-established role as a regulatory cytokine in helminth infections." (PMID 40526709, 2025). "Based on the results of statistical analysis using independent t-tests between leprosy patients with and without helminth infection, a p-value of 0.001 (p < 0.05) was obtained for serum IL-10 levels and 0.0001 (p < 0.05) for serum IL-6 levels." (PMID 41239264, 2025). "In this study, the average IL-10, IL-6, and leptin serum levels in leprosy patients with helminth infections were higher than those without helminth infection." (PMID 41239264, 2025).
helminth infections (continued). "Based on the results of the statistical analysis in this study, there were significant differences in IL-10 (p = 0.001) and IL-6 (p = 0.0001) serum levels between leprosy patients with and without helminth infections." (PMID 41239264, 2025). "Based on an independent t-test, the difference in serum levels of IL-10 and IL-6 in leprosy patients with and without helminth infections was p = 0.001 and p = 0.0001, respectively." (PMID 41239264, 2025). "Only when the effects of both IL-10 and IL-4 are blocked does prophylactic helminth infection fail to restrict disease progression in nonobese diabetic mice." (PMID 38277692, 2024). "Helminth infection did not alter the production of IL-17, IFNγ, or IL-10 by antigen-specific CD4+ T cells in the draining lymph nodes, as determined by re-stimulation of a defined number of cells with recombinant H1." (PMID 36753434, 2023). "The Th2, Tregs, and immunomodulatory cytokines (mainly IL-10, and TGF-β) produced during helminth infection may act as inhibitors of Th1 responses (reduced IFN-γ and TNF-α) required for Mtb infection control and increased the risk of reactivation in LTBI." (PMID 37020538, 2023). "Chronic helminth infections mediate a modified Th2 immune response, resulting in reduced pro-inflammatory cytokines, such as IFN-γ and TNF-α, and an increase in anti-inflammatory cytokines, such as IL-10 and TGF-β." (PMID 35206272, 2022). "In contrast, when helminth infection precedes T. gondii infection, mice display a defective IFN-γ and IL-12 production by CD8+ T cells and cDC1, correlated with an increased IL-4 and IL-10 production leading to an enhanced T. gondii cyst load in the brain of coinfected mice." (PMID 35113966, 2022). "Interestingly, helminth infection or immunization with their antigens diminishes eosinophils, IgE, IL-4 and IL-5 levels while augmenting CD4+ FoxP3+ T cells and IL-10 concentration." (PMID 34360926, 2021). "IL-10, a cytokine with broad immunoregulatory function, is known to inhibit the production of iNOS, IFN-γ, IL-12, TNF-α production and suppresses parasite killing in a variety of protozoan and helminth infections." (PMID 34539633, 2021). "Also, oral helminth infections can control type 1 diabetes through mechanisms that involve both CD4 T cell production of IL-4 and IL-10 acting in an independent and redundant manner." (PMID 30386324, 2018). "Although not specific to type 2 immune responses, IL-10 upregulation during helminth infection appears to have an important role in downregulating both type 1 and type 2 immunity." (PMID 30386324, 2018). "Chronic persistent helminth infection or reinfection may therefore lead to impaired mycobacterial immunity through sustained AAM generation and increased IL-10 production." (PMID 28658262, 2017). "The analysis did not reveal any significant effects of helminth infection, or any other predictor on IL-10 gene expression." (PMID 25372668, 2014). "Our analysis did not reveal any significant effect of the helminth infection or any other predictor on IL-10 gene expression thus supported previous findings of dispensable role of this gene in immune modulation process." (PMID 25372668, 2014). "Maternal Mansonella perstans infection was associated with higher interleukin (IL)-10 responses to both immunogens but no reduction in gamma interferon (IFN-γ), IL-5 and IL-13 responses; other maternal helminth infections showed little effect." (PMID 21040693, 2010). "Helminth infections typically induce modified type 2 immune responses, characterized by the release of effector cytokines interleukin (IL-) 4, IL-5, and IL-13 from Th2 cells and type 2 innate lymphoid cells (ILC), and by heightened production of anti-inflammatory IL-10 by regulatory T (Treg) cells." (PMID 39140728, 2024).